SOD1 (superoxide dismutase 1)
Diseases named in the same sentence as SOD1 in open-access papers (continued):
Sharing a sentence is not in itself a finding about the gene and the disease.
Huntington disease (70 papers, 2009 to 2026). Huntington disease (HD) is a rare neurodegenerative disorder of the central nervous system characterized by unwanted choreatic movements, behavioral and psychiatric disturbances and dementia. "In monogenic diseases like SOD1-related ALS or Huntington's disease, a known mutation can be directly targeted." (PMID 41585268, 2025). "Inefficient microtubule-based transport in axons is linked with several age-related neurodegenerative diseases including Alzheimer’s, Huntington’s disease, and hereditary spastic paraplegia, as well as with ALS caused by mutations in SOD1, TARDBP, and FUS." (PMID 33837088, 2021). "Likewise, vha-6 RNAi reduced the ageing-associated formation of polyQ and mutant superoxide dismutase 1 (SOD1) aggregates in C. elegans models of Huntington’s disease and ALS64,65, respectively." (PMID 40571723, 2025). "Mitochondrial transport deficits are linked with several neurodegenerative disorders, such as Alzheimer’s and Huntington’s disease, hereditary spastic paraplegia, Charcot–Marie–Tooth disease, as well as ALS with SOD1, TARDBP, and FUS mutations, and ALS with hexanucleotide repeats in C9orf72." (PMID 38363426, 2024). "However, metformin has been shown to attenuate the pathology in mouse models of Huntington’s disease and multiple sclerosis, suggesting the need of a functional SOD1 for metformin to exert an anti-oxidant effect." (PMID 39042641, 2024). "Likewise, studies investigating the IRE1 pathway in Huntington’s disease and ALS found that XBP1 deficiency was protective against neuron degeneration in their respective models, and also lead to an increase in autophagy dependent clearance of Htt and SOD-1." (PMID 34063979, 2021). "Significantly, clinical trials have been conducted in patients using ASOs targeting superoxide dismutase 1 (SOD1) in ALS and the mutant huntingtin gene in Huntington’s disease." (PMID 34054431, 2021). "In contrast to mutant SOD1 and Parkin aggregates, COMMD1 has no clear effect on the aggregation of a fragment encoding the N-terminal region of exon 1 of the Huntingtin gene with either 74 or 119 glutamine repeats (HttQ74 and HttQ119) associated with Huntington’s disease." (PMID 24691167, 2014). "The work presented here is also consistent with human post mortem tissue where TDP-43 does not accumulate with Htt in a case study of coexisting Huntington’s disease with ALS52 (although both polyQ repeats and TDP inclusions were present) and is not found in mutant SOD1 inclusions." (PMID 26293199, 2015).
lung carcinoma (69 papers, 2013 to 2026). "Other evidences show that inhibition of SOD1 by ATN-224 induces cell death in various non–small-cell lung cancer (NSCLC) cells, including those harboring KRAS mutations." (PMID 35978820, 2022). "The serum SOD1 concentration appears to be better than the SOD2 concentration for the prediction of all-cause mortality in lung cancer, as demonstrated by our Kaplan–Meier overall survival estimates." (PMID 34832849, 2021). "All-cause mortality in lung cancer was positively associated with serum SOD1 and SOD2 concentrations." (PMID 34832849, 2021). "Additionally, studies have suggested a potential link between SOD1 and tumorigenesis, as elevated SOD1 levels are associated with poorer prognosis for various cancer types, such as breast and lung cancers." (PMID 39290254, 2024). "Here, we found that the treatment of the lung cancer cells with CIGB-552 impaired the SOD1 activity and it could be associated with the accumulation of COMMD1." (PMID 23401744, 2013). "The findings of this study suggest that serum SOD1 concentration could be included in the routine clinical characteristics of lung cancer patients as an additional diagnostic and prognostic biomarker; however, this still required corroboration by further, more detailed studies with larger cohorts." (PMID 34832849, 2021). "Compared with those in normal bronchial epithelial cell lines, SOD1 mRNA and protein levels were found to be significantly elevated in lung cancer cell lines." (PMID 41498040, 2025). "Nevertheless, the majority of previous research has primarily centered on the expression levels of SOD1 in lung cancer and its correlation with prognosis and therapeutic efficacy, with limited probing into the role of SOD1 in modulating radiosensitivity." (PMID 41498040, 2025). "This suggests that β‐Thy effectively counteracts the proliferative advantage conferred by SOD1 in lung cancer cells." (PMID 41498040, 2025). "Lin and colleagues demonstrated that SIRT5 bound to copper/zinc superoxide dismutase (SOD1), desuccinylated SOD1, and activated SOD1 to eliminate ROS and inhibited lung cancer cell growth." (PMID 39781339, 2025). "It is worth highlighting that β‐Thy has been evidenced to interact with SOD1, thereby influencing the radiosensitivity of non‐small cell lung cancer." (PMID 41498040, 2025). "We used two different SOD1 inhibitors, 4,5-dichloro-2-m-tolyl pyridazin-3(2H)-one (also known as lung cancer screen-1 [LCS-1]) and Bis-choline tetrathiomolybdate (ATN-224), which work by different mechanisms." (PMID 38896450, 2024). "According to a report by Glasauer, the inhibition of SOD1 leads to a decrease in the concentration of antiapoptotic factors and to the higher apoptosis of lung cancer cells." (PMID 36985725, 2023). "A recent study also discovered elevated SOD1 expression levels in lung cancer cells, facilitating cell proliferation, invasion, and migration." (PMID 36834640, 2023). "Here, we showed that the depletion of CHI3L1 induces ER stress-mediated lung cancer cell death through SOD1 upregulation." (PMID 37215572, 2023). "In lung cancer patients, erythrocyte SOD1 activities are significantly higher than those in normal controls." (PMID 35978820, 2022). "By combining affinity proteomics and gene expression analysis, a small molecule, referred to as lung cancer screen 1 (LCS-1) is identified as SOD1 inhibitor and reduces the growth of lung adenocarcinoma cell lines." (PMID 35978820, 2022). "According to multiple Cox regression models predicting lung cancer mortality, only serum concentrations of SOD1 and SOD2 and advanced clinical (III–IV) stages of disease remained statistically significant." (PMID 34832849, 2021). "Increased serum SOD1 concentration per 1 pg/mL and SOD2 per 1 ng/mL were significantly associated with a 0.4 and 19% higher HR, respectively, for all-cause mortality in lung cancer patients." (PMID 34832849, 2021).
lung carcinoma (continued). "The results showed that SOD1 knockdown attenuated the growth of mouse and human KP and KL lung cancer cells." (PMID 33859191, 2021). "Most importantly, our analysis indicated that the serum SOD1 and SOD2 concentrations are good prognostic parameters of all-cause mortality in lung cancer." (PMID 34832849, 2021). "Small-molecule inhibitors targeting SOD1 have been shown to effectively suppress the growth of lung cancer cells in vitro and xenograft tumors in vivo." (PMID 33859191, 2021). "Together, these observations indicate that PeBoW complex is a key effector for SOD1 to control oncogenic KRAS-driven lung cancer cell proliferation through pre-rRNA processing and 60S ribosome biogenesis." (PMID 33859191, 2021). "The models confirmed that elevated serum SOD1 and SOD2 concentrations significantly increased the HR of all-cause mortality in lung cancer patients." (PMID 34832849, 2021). "We have recently found that a fraction of mouse SOD1 localizes to the nucleolus and facilitates the generation of 60S ribosomal subunits in lung cancer cells." (PMID 33981726, 2021). "Only serum SOD1 concentration significantly differentiated lung cancer patients from control subjects, with a cutoff value of 175.03 pg/ml, an AUC of 0.684 (0.608–0.759), and a Youden’s index value of 31%." (PMID 34832849, 2021). "In conclusion, higher SOD1 and SOD2 concentrations were shown to positively affect the risk of all-cause mortality in lung cancer patients, but the serum SOD1 concentration appears to be a better predictor than the serum SOD2 concentration." (PMID 34832849, 2021). "Our results provide in vivo genetic evidence for the critical role of SOD1 in lung cancer tumorigenesis." (PMID 33859191, 2021). "Collectively, the present study indicates that KRAS-driven lung cancer cells are critically dependent on SOD1 to maintain nucleolar hypertrophy and proliferative capacity." (PMID 33859191, 2021). "A survey of SOD isoform concentrations in the sera of lung cancer patients revealed significant alterations in both SOD1 and SOD2 levels in comparison with control subjects." (PMID 34832849, 2021). "To ask the role of SOD1 in different KRAS mutant lung cancer cells, we knocked down SOD1 in both KP and KRAS-LKB1 (KL) mouse and human NSCLC cell lines." (PMID 33859191, 2021). "Serum SOD1 and SOD2 concentrations were shown to positively affect all-cause mortality in lung cancer patients, but SOD1 seems to be a better predictor than SOD2." (PMID 34832849, 2021). "Previous studies have shown that inhibiting SOD1 either by shRNA or the SOD1 inhibitor ATN-224 drastically reduces the ability of the lung carcinoma cell line A549 to form colonies on soft agar." (PMID 29891006, 2018). "SOD1 inhibition is considered to induce cell death potentially, and targeting SOD1 in lung cancer has been reported." (PMID 30279365, 2018). "The C8-ceramide-induced treatment modulated the levels of SOD1 and cyclin D1 in H1299 lung cancer cells on a protein level, which was examined by Western blotting in the present study." (PMID 30279365, 2018). "According to some reports, the inhibition of SOD1 leads to a decrease in the concentration of antiapoptotic factors, and finally to the apoptosis of lung cancer cells." (PMID 30347787, 2018). "Immunoblotting detection of Ac-SOD1 level from those cells revealed that the basal level of Ac-SOD1 was correlated with the sensitivity to CPT treatment in lung cancer cells." (PMID 26008972, 2015). "They reported in their study that overexpression of SOD1 promotes lung cancer cells growth and reduce apoptosis." (PMID 24955214, 2014). "They showed that inhibition of SOD1 either by shRNA or the SOD1 inhibitor ATN-224 drastically reduces the ability of the lung carcinoma cell line A549 to form colony on soft agar." (PMID 24955214, 2014). "Next, we considered it important to determine the relevance of this accumulation in the enzymatic activity of SOD1, and the antioxidant capacity of the lung cancer cells." (PMID 23401744, 2013).
lung carcinoma (continued). "A study concluded that serum SOD1 concentration was a better predictor than serum SOD2 concentration, however both SOD1 and SOD2 concentrations have been demonstrated to positively impact the risk of all-cause mortality in patients with lung cancer." (PMID 40867576, 2025). "Intriguingly, the role of SOD1 in oncological biology is not limited to lung cancer alone." (PMID 39123408, 2024). "SOD1, superoxide dismutase, drives ribosome biogenesis in Kras-driven lung cancer models in mice." (PMID 36497261, 2022). "Moreover, in this study, the cutoff values of serum SOD1 and SOD2 concentrations significantly differentiated lung cancer patients from the control group (SOD1), and predicted mortality in the studied group of lung cancer patients (SOD1 and SOD2)." (PMID 34832849, 2021). "Higher concentrations of SOD1 and ceruloplasmin may indicate an increased Cu demand—and, therefore, circulation of Cu—in patients with lung cancer." (PMID 34832849, 2021). "Furthermore, high levels of SOD1 promoted lung cancer cell proliferation and metastasis, while miR-409-3p inhibited SOD1 activity through binding to its 3′ UTR." (PMID 32391354, 2020). "Based on this hypothesis, we used GSCALite software to identify 90 lung cancer-related transcription factors related, among which only SETDB1 was associated with both SOD1 and miR-409-3p." (PMID 32391354, 2020). "Notably, SOD1, a copper-dependent enzyme, was reported to participate in lung cancer growth and has become a significant therapeutic target." (PMID 32195181, 2020). "Apart from colon cancer, we also tested whether basal Ac-SOD1 levels were correlated with the sensitivity to CPT treatment in lung cancer cells." (PMID 26008972, 2015). "Furthermore, their research demonstrated that the administration of CSF-1 could effectively suppress the overexpression of SOD1, slowing tumor growth in lung cancer." (PMID 39123408, 2024). "(E) Immunoblot of WT and PPM1D-mutant OCI-AML2 after transduction with the empty vector (EV) control and after SOD1 deletion (left) or after treatment with SOD1 inhibitors for 16 hr (right, ATN-224 12.5 μM, lung cancer screen-1 [LCS-1] 1.25 μM)." (PMID 38896450, 2024). "The double depletion of CHI3L1 and SOD1 decreased the ER chaperone proteins (Grp78 and PDI) and PERK signaling proteins compared with the depletion of CHI3L1 in lung cancer cells and metastatic lung tumor tissues." (PMID 37215572, 2023). "Serum total SOD activity and SOD1, SOD2, albumin, CRP, and ceruloplasmin concentrations were determined in lung cancer patients (n = 190) and control subjects (n = 52)." (PMID 34832849, 2021). "To investigate the molecular function of SOD1 in lung cancer cells, we derived NSCLC cell lines from Sod1+/+ or Sod1Flox/Flox KP lung tumors." (PMID 33859191, 2021). "Mechanistically, SOD1 regulates co-localization of PeBoW with and processing of pre-rRNA, and maturation of cytoplasmic 60S ribosomal subunits in KRAS mutant lung cancer cells." (PMID 33859191, 2021). "Instead, SOD1 is crucial for sustaining the growth of lung cancer cells in KRAS-driven lung tumors in a GEM model as well as cultured human and mouse lung cancer cells." (PMID 33859191, 2021). "In agreement with SOD1 as a key factor for lung cancer cell proliferation, SOD1 level was also positively correlated with that of PCNA, a proliferation marker, Moreover, NSCLC tumors with high SOD1 expression correlated with poor survival." (PMID 33859191, 2021). "The median serum SOD1 and SOD2 concentrations were significantly higher in lung cancer patients compared to control subjects (218.9 vs. 141.0 pg/mL, and 1.30 vs. 0.78 ng/mL, respectively)." (PMID 34832849, 2021). "Collectively, our study unravels a nuclear SOD1 function essential for ribosome biogenesis and proliferation in KRAS-driven lung cancer." (PMID 33859191, 2021).
lung carcinoma (continued). "The superoxide dismutase SOD1 is highly expressed in lung cancer but its role has not fully investigated yet." (PMID 33859191, 2021). "Our findings confirm the first study’s hypothesis to a good extent: SOD1 and SOD2 concentrations were higher in lung cancer patients than in the control group." (PMID 34832849, 2021). "Despite this progress, the role of SOD1 in lung cancer has not been studied genetically in relevant animal models in vivo." (PMID 33859191, 2021). "However, serum SOD1 and SOD2 concentrations significantly predicted mortality in lung cancer patients." (PMID 34832849, 2021). "Moreover, most previous studies concerning SOD in lung cancer focused only on one or two parameters: total SOD, or SOD1 and SOD2 concentrations." (PMID 34832849, 2021). "The nuclear and nucleolar, not cytoplasmic, form of SOD1 is essential for lung cancer cell proliferation." (PMID 33859191, 2021). "Consistently, the decrease of SOD1 and SOD2 ratio was also observed in H1299 cells following C8-ceramide treatment, suggesting that the anti-lung cancer effects of C8-ceramide may be closely correlated with the mechanism of SOD1 to SOD2 switch." (PMID 30279365, 2018). "We further show that two SOD1 inhibitors (ammonium tetrathiomolybdate [ATTM] and Lung Cancer Screen-1 [LCS-1]) and one chemical mimetic (2-methoxyestradiol [2ME2]) phenocopy the SOD1 silencing results by inducing preferential killing within BLM- and CHEK2-deficient cells." (PMID 26318585, 2015). "SOD1 in lung cancer cells promotes growth without affecting cell cycle progression." (PMID 37886979, 2023). "However, the role of SOD1 in lung cancer has not been investigated genetically." (PMID 33859191, 2021). "In the present investigation, levels of the antioxidant enzyme SOD1, but not those of SOD2 or catalase, were significantly greater in the tumors of the lung cancer-bearing mice treated with the monoclonal antibodies." (PMID 31487876, 2019). "Nonetheless, they are counter to what shown in mice with lung cancer-induced cachexia in which protein levels of SOD2 were significantly decreased in their respiratory and limb muscles, while levels of SOD1 were not modified by cachexia in the same animals." (PMID 29255650, 2017). "Protein levels of SOD1 (rank: 3) were significantly higher in both tumor and non-tumor lung specimens of COPD patients than in lung cancer patients with no COPD." (PMID 28873096, 2017). "However, no research on disturbances in serum SOD1 and SOD2 concentrations has been performed in lung cancer patients." (PMID 34832849, 2021). "Additionally, neither serum total SOD activity nor serum SOD1 and SOD2 concentrations were found to be useful indicators in determining clinical stage IV lung cancer." (PMID 34832849, 2021).
myocardial infarction (67 papers, 2011 to 2026). Gross necrosis of the myocardium, as a result of interruption of the blood supply to the area, as in coronary thrombosis. "Experimental studies have demonstrated that SOD1 works as an antioxidant and protects cardiomyocytes from oxidative stress in a myocardial infarction model." (PMID 27755600, 2016). "SOD1 overexpression, RELA blockade, and diminished MyD88-mediated inflammation can enhance functional and metabolic recovery and greatly decreased myocardial infarction, while ADIPOR2 is required for revascularization." (PMID 32565767, 2020).
liver fibrosis (63 papers, 2009 to 2025). "SOD-1 knockout mice were shown to cause liver fibrosis by promoting MMP (MMP 2 and 9) and TIMP (TIMP1) protein expression; collagen accumulated in the liver." (PMID 37298640, 2023). "FAN administration alleviated the inhibition of the Nrf2 pathway in the liver specimens of rodents with hepatic fibrosis by increasing the Nrf2 expression and its downstream detoxification enzymes’ (HO-1, SOD1, and CAT) protein levels and decreasing the protein level of Keap1." (PMID 40910002, 2025). "Simultaneously, the antioxidant prowess of hepatocytes in these mice experienced compromise due to a marked reduction in SOD1 and SOD2 expression, aligning with outcomes observed in CCl4-induced liver fibrosis in rats." (PMID 38132319, 2023).